LBP (lipopolysaccharide binding protein)
Diseases named in the same sentence as LBP in open-access papers (continued):
Sharing a sentence is not in itself a finding about the gene and the disease.
Insulin resistance (22 papers, 2012 to 2026). Increased resistance towards insulin, that is, diminished effectiveness of insulin in reducing blood glucose levels. "Moreover, the significant positive association of serum LBP levels and future insulin resistance was attenuated after adjusting for serum hs-CRP." (PMID 36567128, 2022). "The significant positive association between serum LBP and future insulin resistance, represented by the geometric averages of HOMA-IR at the follow-up survey, was also observed in the multivariable-adjusted analysis, but disappeared after additional adjustment for serum hs-CRP." (PMID 36567128, 2022). "This imbalance is associated with systemic inflammation and insulin resistance, evidenced by elevated levels of C-reactive protein (CRP), interleukin-6 (IL-6), tumor necrosis factor-alpha (TNF-α), and lipopolysaccharide-binding protein (LBP)." (PMID 40308637, 2025). "The present study is the first to demonstrate the direct impact of PSE and LUT on reducing intestinal permeability in MetS-like mice with insulin resistance, as shown by decreased plasma LBP (an intestinal permeability marker)." (PMID 40732915, 2025). "In high fat diet obese mice with insulin resistance, Prevotella was deemed as pro-inflammatory and, of note, its abundance in our study correlated with serum LBP." (PMID 33639944, 2021). "Meanwhile, metabolic beneficial effects of LcS supplement were observed in high-fat diet (HFD)-induced and genetic db/db obese mice, in which LcS supplementation significantly improved insulin resistance and lowered plasma levels of LBP." (PMID 29035308, 2017). "Serum LBP levels were positively correlated with body mass index, triglycerides, high-sensitivity C-reactive protein, and insulin resistance index and were negatively correlated with high-density lipoprotein cholesterol." (PMID 28486964, 2017). "Importantly, we also detected that circulating levels of endotoxin, LBP, zonulin and S100A8 were associated with insulin resistance, due to the positive correlation with insulin levels and HOMA index and the negative association with QUICKI index." (PMID 38315242, 2024). "Additionally, 4 weeks of HIIT can decrease the F/B ratio in insulin-resistant patients, reduce serum levels of TNF-α, C-reactive protein (CRP), and lipopolysaccharide-binding protein (LBP), improving systemic insulin resistance." (PMID 39834360, 2024). "In conclusion, BBR can significantly reduce the abundance of Proteobacteria, such as Desulfovibrio, Enterobacter cloacae, and inhibit LPS production, effectively prevent serum LBP elevation, regulating intestinal permeability, attenuating insulin resistance and improve metabolic endotoxemia." (PMID 36093200, 2022). "In patients with the metabolic syndrome, increased blood levels of LPS and of the most important LPS ligand, the LPS binding protein (LBP), have been described and found to be correlated with insulin resistance, further supporting the detrimental role of chronic inflammation in glucose metabolism." (PMID 30764482, 2019). "Taken together, results of our study suggest that endotoxin and LBP plasma levels are strongly related to proinflammatory changes even in the early stages of NAFLD, while sCD14 levels seem to be associated with markers of insulin resistance." (PMID 28880885, 2017).
metabolic syndrome (22 papers, 2013 to 2025). A cluster of metabolic risk factors for CARDIOVASCULAR DISEASES and TYPE 2 DIABETES MELLITUS. "In other conditions, such as autism, stress, or metabolic syndrome, elevated levels of markers like lipopolysaccharide-binding protein (LBP) or soluble CD14 (sCD14) have been directly linked to the leaky gut process." (PMID 39767686, 2024). "Higher levels of chemerin and lipopolysaccharide-binding protein were associated with a greater number of metabolic syndrome components." (PMID 35327393, 2022). "Translocated LPS in the systemic circulation binds to LPS-binding protein (LBP), which is a marker for metabolic syndrome, and our previous study showed clear positive associations between plasma levels of interleukin-6 and LBP in patients with T2DM." (PMID 33567701, 2021). "Among the components of metabolic syndrome, serum LBP concentrations were independently associated with abdominal obesity and low HDL-cholesterol levels." (PMID 23349936, 2013). "Multivariate analysis of factors associated with serum lipopolysaccharide-binding protein (LBP) concentrations: metabolic syndrome components." (PMID 23349936, 2013). "Serum LBP levels correlate positively with metabolic syndrome, atherosclerosis, and type 2 diabetes." (PMID 39997462, 2025). "People with psoriasis and concomitant metabolic syndrome have also been observed to have higher levels of lipopolysaccharide-binding protein (LBP), an indicator of serum LPS, a toxic bacterial byproduct." (PMID 37623895, 2023). "Jialal I, Devaraj S, Bettaieb A, Haj F, Adams-Huet B. Increased adiose tissue secretion of fetuin-A, lipopolysaccharide-binding protein and high-mobility group box protein 1 in metabolic syndrome." (PMID 35195203, 2022). "Similarly, the association between metabolic syndrome and LBP concentration was independent of confounders (data not shown)." (PMID 23349936, 2013). "Oral administration of 6.5 x 109 colony forming units (CFUs) of Lactobacillus casei Shirota in patients with metabolic syndrome did not influence lipopolysaccharide-binding protein (LBP) compared with controls." (PMID 36259581, 2022).
diabetes (20 papers, 2017 to 2025). "If so, lipopolysaccharide-binding protein might become a treatment option for diabetes and a way to prevent the associated coagulopathy." (PMID 30268122, 2018). "Intestinal permeability was increased in diabetes as assessed by measurement of plasma lipopolysaccharide binding protein (p < 0.01) and plasma endotoxin (p < 0.05)." (PMID 38902253, 2024). "Patients with type 2 diabetes mellitus have significantly higher levels of the LPS-binding protein (LBP), and LBP was positively correlated with the glycated hemoglobin, body mass index, and inflammatory markers of study participants." (PMID 36093202, 2022). "Other beneficial actions were reported such as decrease lipopolysaccharide-binding protein in female mice, diminished histopathological lesions of inflammatory infiltrations in distal colon, or modulating diabetes-related genes expression in diabetic mice." (PMID 32102343, 2020). "When compared to the normal group, the diabetes model group's mRNA expression levels for LBP, TLR4, MyD88, NF-κB, AP-1, and IRF-3 were significantly higher (p < 0.05); after taurine treatment, we discovered that these mRNA levels had decreased significantly (p < 0.05)." (PMID 38560269, 2024). "Indeed, serum concentrations of LBP and sCD14 have been demonstrated to decrease or remain unchanged under conditions of autoimmunity, such as type 1 diabetes mellitus, despite the presence of elevated levels of LPS." (PMID 33301421, 2021). "Notably, LBP is also regarded as an acute phase protein participating in immune response in different clinical settings, such as in patients with coronary artery disease, diabetes, and pancreatitis." (PMID 40966311, 2025). "Additionally, it remains unclear whether chronic upregulation of LBP contributes to the development of stress-related metabolic disorders, such as diabetes and cardiovascular disease." (PMID 38615060, 2024). "Lipopolysaccharide-binding protein (LBP), an acute-phase protein mainly secreted by the liver, modulates the LPS-induced immune response; particularly, circulatory LBP levels are considerably increased in patients with type 2 diabetes mellitus, especially those with morbid obesity." (PMID 34086828, 2021). "Accordingly, serum LBP levels negatively correlated with FBG (r = −0.19, p = 0.01), HbA1c (r = −0.26, p = 0.003), diabetes duration (r = −0.20, p = 0.034), and albuminuria (r = 0.29, p = 0.042) in the bivariate correlation analysis." (PMID 38139003, 2023). "We examined the differences in the levels of zonulin, LBP, β-glucan, sCD14, and IL-6 between hospitalized patients (moderate and severe groups) who had diabetes or not, or patients who had high blood pressure or not." (PMID 34177935, 2021). "Human lipopolysaccharide-binding protein (LBP) and vitamin D binding protein (VTDB) were suppressed in patients without diabetes and were associated with severe coronary artery stenosis." (PMID 34948066, 2021).
atherosclerosis (19 papers, 2014 to 2025). A disease characterized by the build-up of fatty material and calcium deposition in the arterial wall resulting in partial or complete occlusion of the arterial lumen. "LBP serum levels have been proposed as a useful diagnostic marker in both urinary infections in children and atherosclerosis, as well as a prognostic marker in acute appendicitis." (PMID 26222498, 2015). "Furthermore, in support of previous studies that showed that LBP (marker of circulating endotoxaemia) was an independent predictor of atherosclerosis, this present study also established an association between elevated LBP levels and CIMT." (PMID 32649699, 2020). "CRP, LBP, and OPG are probably only markers of ongoing process of atherosclerosis that reflect vitamin D deficiency." (PMID 37623831, 2023). "LPS activates immune cells via LPS-binding protein (LBP)/soluble CD14 (sCD14)/toll-like receptor-4 (TRL4) signalling and has been implicated in the etiology of atherosclerosis among other inflammatory conditions." (PMID 34797867, 2021). "LBP were mainly present in NF-kappa B signaling pathway and lipid and atherosclerosis." (PMID 36874092, 2023). "Besides, another metabolite, LPS, involved in infectious diseases has recently shown to have some effects on atherosclerosis based on in experimental and clinical trials by binding to various proteins, such as LBP, CD14, TLR-4, and MD-2." (PMID 34414217, 2021). "A recent study also showed that serum LBP levels were positively correlated with subclinical atherosclerosis, as assessed by carotid intima-media thickness, in healthy individuals, independent of body mass index (BMI) and high-sensitivity C-reactive protein (hs-CRP) level." (PMID 28486964, 2017). "The KEGG path view suggests that LBP, MMP9, APOB, IL6, and RAP1B are involved in lipid metabolism and atherosclerosis." (PMID 41221287, 2025). "These included proteins involved in atherosclerosis/inflammation (e.g. GDF-15, lipopolysaccharide binding protein, and CD14), extracellular matrix [matrix metalloproteinase-7 (MMP7)], heart failure [N-terminal pro-B-type natriuretic peptide (NT-proBNP)], and renal insufficiency cystatin C (CST3)." (PMID 39660078, 2024). "Moreover, the effects of nLDL on the inflammatory ability of human monocyte subpopulations are enhanced by LPS, confirming previous evidence suggesting that nLDL and LBP form a negative loop that contributes to atherosclerosis." (PMID 34439835, 2021).
Stroke (18 papers, 2015 to 2024). Sudden impairment of blood flow to a part of the brain due to occlusion or rupture of an artery to the brain. "In a study measuring plasma LBP levels on days one to four after stroke, it was found that the highest level of plasma LBP after stroke was observed on day four in patients with stroke-associated pneumonia." (PMID 36699006, 2022). "In patients with acute ischemic stroke, lipopolysaccharide-binding protein (LBP) was associated with both systemic inflammation and a predictive risk of post-stroke infections, which indicates a dysfunction in the intestinal barrier." (PMID 30537997, 2018). "LPS levels correlate with CRP and LBP for all causes of stroke." (PMID 33753837, 2021). "Another study has also revealed that fecal transplants of mice from patients with cognitive impairment after stroke showed worse cognitive function, higher levels of LBP and gut toll-like receptor 4, and more severe gut disruption." (PMID 37113132, 2023). "In contrast to iFABP, LBP (which is ~ 4-fold larger) is only elevated in males with stroke, suggesting that gut permeability is likely more severe in males." (PMID 33451354, 2021). "We aimed to determine if plasma levels of bacterial lipopolysaccharide (LPS) and lipoteichoic acid (LTA) are associated with different causes of stroke and correlate with C-reactive protein (CRP), LPS-binding protein (LBP), and the NIH stroke scale (NIHSS)." (PMID 33753837, 2021). "Since we did not measure lipoprotein levels, the relationship between LPS, LBP, lipoproteins and cholesterol in stroke patients remains to be elucidated." (PMID 33753837, 2021). "That LPS drives LBP expression in stroke is supported by human studies where LPS infusion increases LBP levels." (PMID 33753837, 2021). "LPS levels correlated with CRP and LBP levels in stroke and TIA." (PMID 33753837, 2021). "Lipopolysaccharide-binding protein, as a type I acute phase response protein, was considered as a marker for infections in stroke-associated pneumonia but with no data presented on microbiological findings." (PMID 32508734, 2020). "We hypothesized that levels of lipopolysaccharide binding protein (LBP), interleukin-10 (IL-10), IL-6 and C-reactive protein (CRP) are early predictors for the development of stroke-associated infection." (PMID 25613713, 2015). "In all stroke groups, regardless of the presence of AF, an increase in proteins (CRP, LBP, and A1AG1) involved in the inflammatory response was observed in patients with stroke compared to the control group." (PMID 38886511, 2024). "Part of the variance (between 45–48.3%) in the peak DRS score measured 2–3 days post-surgery was explained by independent effects of IgA directed to LPS and LBP (or bacterial CDT), baseline DRS scores, and previous mild stroke." (PMID 38379706, 2024). "Interestingly, in patients with stroke and AF, proteins involved in the inflammatory response (CRP, LBP, and A1AG1) were significantly increased compared to those without AF, and TTR and RBP were significantly decreased." (PMID 38886511, 2024). "Hence, in clinical diagnosis and treatment, serum marker tests for A2M, LBP, CTSG, CST3, and FABP1 should be prioritized in patients with a high suspicion of stroke for early detection and timely intervention." (PMID 38090270, 2023). "We hypothesized that early levels of the inflammatory and anti-inflammatory markers LBP, IL-10, IL-6 and CRP are biomarker candidates for the prediction of post-stroke infections in acute ischemic stroke patients." (PMID 25613713, 2015). "A1AG1, CRP, and LBP were upregulated, while TTR, ApoC2, and RBP4 were downregulated in patients with stroke and AF, compared to patients with stroke without AF." (PMID 38886511, 2024).
Stroke (continued). "In other words, through serum protein profiling in patients with stroke and AF and patients with stroke but without AF, traces of inflammatory activity such as CRP, LBP, and A1AG1 were confirmed in patients with stroke and AF, and changes in thyroid hormone transport protein." (PMID 38886511, 2024).
Cirrhosis (17 papers, 2011 to 2025). A chronic disorder of the liver in which liver tissue becomes scarred and is partially replaced by regenerative nodules and fibrotic tissue resulting in loss of liver function. "High serum concentrations of lipopolysaccharide binding protein (LBP) are associated with decreased survival in patients with decompensated cirrhosis, and Lbp knockdown increases liver inflammation in mice fed a methionine- and choline-deficient (MCD) diet." (PMID 40595432, 2025). "Surrogate markers of bacterial gut barrier dysfunction and bacterial translocation like ZFP, LBP and EndoCAb appear of limited use in advanced stages of cirrhosis and are confounded by hepatic synthesis capacity, portal congestion and acute phase responses." (PMID 40317887, 2025). "This study suggests that zonulin and LBP are potential targets of renal outcomes in decompensated cirrhosis." (PMID 37567912, 2023). "And lastly, it has been reported that in rats with cirrhosis, BCAAs can reduce the protein expression of LBP and TLR4, which are the driving factors leading to immune cell exhaustion." (PMID 37252239, 2023). "We demonstrated the essential roles of zonulin, LPS, and LBP in renal outcomes of patients with cirrhosis." (PMID 37567912, 2023). "Bacterial translocation, defined as high circulating LBP level in cirrhosis, is the main contributor to the increased proliferation and apoptosis, and decreased activation of naíve and effector memory Th cells." (PMID 32138352, 2020). "Particularly, the elevation of splenic LBP as well as up-regulation of splenic ADRB1 and ADRB2 expression indicated the involvement of the spleen in the pathogenesis of cirrhosis-associated immune dysfunction." (PMID 32138352, 2020). "In this study, we have shown that the AA genotype of the ApaI polymorphism is related to decreased levels of platelets and increased levels of LBP, which are consistent with the progression of cirrhosis and portal hypertension development." (PMID 30218108, 2018). "The serum LBP levels were significantly reduced from 33.6±7.6 to 26.4±7.7 μg/mL in non-cirrhosis group and from 35.4±7.0 to 28.2±5.5 μg/mL in cirrhosis group (p-value < 0.001 and 0.002)." (PMID 28107471, 2017). "According to liver fibrosis and cirrhosis, LBP levels were both gradually declined especially in liver fibrosis and cirrhosis group (tested by ANOVA test, p-values = 0.023)." (PMID 28107471, 2017). "Compared to healthy controls, patients with cirrhosis had higher circulating levels of LBP and IL-10, an expansion of peripheral blood CD14+ monocytes with low HLA-DR expression and an increased fraction of CD25-positive CD4+ and CD8+ T cells." (PMID 23446058, 2013). "Concomitantly, IL-10 serum concentrations were elevated in patients with cirrhosis showing a trend of a positive linear correlation between serum IL-10 and LBP." (PMID 23446058, 2013). "This study used markers involved in leaky gut mechanisms, including zonulin, LPS, and LBP, to predict AKI and HRS–AKI in patients with advanced cirrhosis." (PMID 37567912, 2023). "This study found that zonulin, LPS, and LBP are reliable markers for AKI and HRS–AKI in patients with cirrhosis." (PMID 37567912, 2023). "Compared to WT-sham mice, higher serum LPS binding protein (LBP) levels, higher MLN culture positive rates, and lower cirrhosis dysbiosis ratios (CDR) were observed in WT-BDL mice." (PMID 33513830, 2021). "Presence of LPS and the LPS-binding protein LBP is supposed to be due to bacterial translocation and increased gut-blood permeability in patients with cirrhosis." (PMID 30183743, 2018). "Univariate RDA analysis revealed that cirrhosis, PPI intake, beta blockers, statins, platelet function inhibitors, BMI, CRP, INR, calprotectin, zonulin, DAO, lipopolysaccharide-binding protein (LBP) and sCD14 were potential explanatory variables for microbiome composition with a p-value < 0.1." (PMID 32906634, 2020).
Cirrhosis (continued). "Serum LBP levels in patients with or without HCV-coinfection were similar: it must be considered that decompensated cirrhosis, a situation in which bacterial translocation is characteristic, was an exclusion criterion." (PMID 25775475, 2015). "However, LBP levels were slightly increased in non-liver fibrosis and cirrhosis group that might be the limited sample size." (PMID 28107471, 2017). "LBP as a marker for bacterial translocation was not different in the four groups, but soluble CD14 (sCD14) was significantly elevated in SC-CIP and cirrhosis compared to healthy controls (p < 0.001) and in cirrhosis compared to CIP controls (p = 0.01)." (PMID 32906634, 2020). "When patients with decompensated cirrhosis were stratified for the presence and severity of ACLF, we did observe a strong‐stage dependent decline in ZFP across the stages AD, ACLF grade 1, and ACLF grade 2/3, while none were observed for PV‐1, EndoCAb IgA, LBP, or I‐FABP." (PMID 40317887, 2025).